PTPN2 (protein tyrosine phosphatase non-receptor type 2)
Diseases named in the same sentence as PTPN2 in open-access papers (continued):
Sharing a sentence is not in itself a finding about the gene and the disease.
tumor (continued). "The diversity of PTPN2 effects in different types of tumors makes it a potential target for tumor immunotherapy." (PMID 36077422, 2022). "In this review, we attempt to summarize the important functions of PTPN2 in terms of its structural and functional properties, inflammatory reactions, immunomodulatory properties, and tumor immunity." (PMID 36077422, 2022). "PTPN2 is a target for enhancing T cell-mediated anti-tumor immunity and CAR-T cell therapy of solid tumors." (PMID 35461336, 2022). "Recently in human colorectal cancer (CRC) tissue, the higher expression of PTPN2 with the reduction of anti-tumor immunity." (PMID 35154122, 2022). "PUN mitigates inhibition of the JAK/STAT pathway by knocking out the protein tyrosine phosphatase PTPN2 in tumor cells, which relies on IFN-γ to promote antigen presentation and growth inhibition, further amplifying adaptive immunity to PD-L1 blockade." (PMID 35300341, 2022). "For example, the deletion of PTPN2 in tumor cells enhances the efficacy of immunotherapy by enhancing interferon-γ-mediated effects on antigen presentation and growth inhibition." (PMID 36077422, 2022). "Yet, because of PTPN2’s role in maintaining peripheral tolerance, future therapeutic efforts should consider tumor microenvironment specific targeting and be cognizant of immune related adverse events." (PMID 35911672, 2022). "Since PTPN2 influences the production, differentiation, and distribution of immune cells, researchers have turned the spotlight to the role of PTPN2 in the anti-tumor immune response." (PMID 36077422, 2022). "Inhibition of PTPN2 can alleviate the inhibition of the JAK/STAT pathway and promote tumor susceptibility to CD8+ T cells dependent on IFN-γ, thereby further amplifying the adaptive immune response." (PMID 35300341, 2022). "PTPN2 deletion of the immune system also resulted in MC38 tumor clearance and improved PD-1 checkpoint blockade responses to B16 tumors." (PMID 36077422, 2022). "The diversity of PTPN2’s effects in different types of tumor makes it a potential target for tumor immunotherapy." (PMID 36556168, 2022). "Downregulation of PD-L1 and PTPN2 relieved the immunosuppressive microenvironment, amplifying anti-tumor immune responses." (PMID 35918694, 2022). "PTPN2 deletion in tumor cells improves immunotherapy effectiveness by boosting interferon-γ-mediated signaling and growth suppression." (PMID 36077422, 2022). "Here, we reviewed recent research concerning the role and impact of PTPN2 on inflammatory/immune responses and tumor therapy to achieve better application of PTPN2." (PMID 36077422, 2022). "Deletion of PTPN2 in tumor cells increased IFN-γ signaling and antigen presentation to T cells, along with amplified growth arrest in response to cytokines, suggesting its therapeutic potential in potentiating immunotherapy efficacy." (PMID 36077422, 2022). "Although a large number of previous studies have confirmed the tumor suppressive effects of PTPN2 in human cancers, PTPN2 has some degree of pro-cancer effects and predicts a poor prognosis, as more and more comprehensive and detailed studies have emerged." (PMID 36077422, 2022). "Through active and passive tumor targeting in vivo, the accumulation of nanoparticles in tumor led to the decrease of Ptpn2 protein by Cas9-Ptpn2 plasmid in the nanocarrier." (PMID 34490227, 2021). "The CRISPR/Cas9 targeting PD‐L1 and PTPN2 was only activated in tumor tissues benefiting from the programmable unlocking properties of PUN in response to internal stimuli and external triggers." (PMID 34258164, 2021). "For example, the tyrosine phosphatase PTPN2, an adjacent coding gene of lncRNA TCONS_00026679, has been demonstrated to be a tumor suppressor in T-ALL." (PMID 34112247, 2021). "The efficacy of PD-1 immune therapy has also been shown to depend on interferon gamma (IFNγ) sensing by tumor cells in the tumor microenvironment, which can be regulated by tyrosine-protein phosphatase non-receptor type 2 (Ptpn2)." (PMID 34912335, 2021).
tumor (continued). "Here, we report that PTPN2 deletion in T cells enhances cancer immunosurveillance and the efficacy of adoptively transferred tumour‐specific T cells." (PMID 31803974, 2020). "The potential for inflammatory complications, including cytokine release syndrome, precludes the utility of PTPN2 inhibitors for systemic therapy and the promotion of T‐cell‐mediated anti‐tumour immunity." (PMID 31803974, 2020). "Recent researches demonstrated that PTPN2 deletion can enhance the effectiveness of anti-tumor immunity." (PMID 32536826, 2020). "Consistent with this, our studies herein demonstrate that the deletion of PTPN2 in T cells enhances cancer immunosurveillance and the anti‐tumour activity of adoptively transferred T cells." (PMID 31803974, 2020). "To explore this further and the influence of PTPN2 deficiency on CAR T‐cell memory, we re‐implanted HER‐2+ tumour cells into control HER‐2 transgenic mice, or those mice in which HER‐2+ tumours had been previously cleared by PTPN2‐deficient HER‐2 CAR T cells." (PMID 31803974, 2020). "Taken together, these results are consistent with PTPN2 deficiency increasing the functional activity and attenuating the tolerisation of naïve CD8+ T cells to suppress tumour growth." (PMID 31803974, 2020). "Our findings define PTPN2 as a target for bolstering T‐cell‐mediated anti‐tumour immunity and CAR T‐cell therapy against solid tumours." (PMID 31803974, 2020). "Taken together, these results demonstrate that PTPN2 deficiency promotes the LCK‐dependent activation of CAR T cells and overcomes the immunosuppressive tumour microenvironment to eradicate solid tumours in vivo." (PMID 31803974, 2020). "While few papers attribute a tumor-suppressive function to PTPN2, many studies support its oncogenic role." (PMID 33003469, 2020). "Studies have shown that deletion of PTPN22 or PTPN2 in CD8 T cells improved tumor clearance in a number of mouse tumor models." (PMID 33425916, 2020). "Patients with a high expression of PTPN2 tend to have a poor prognosis, suggesting that PTPN2 can promote tumor development." (PMID 33122197, 2020). "The results of this study have established the importance of PTPN2 in T‐cell immunosurveillance and defined a novel target for bolstering the anti‐tumour activity of T cells, especially in the context of adoptive T‐cell therapy." (PMID 31803974, 2020). "Since PTPN2 regulates the transcription of several oncoproteins, PTPN2 has been defined as a tumour suppressor." (PMID 32285621, 2020). "The rate of distant recurrences was similar for systemically untreated patients with high-expressing PTPN2 tumours as well as low-expressing (high vs low, HR = 1.22, 95% CI 0.80–1.86, P = 0.37)." (PMID 30515568, 2019). "PTPN2 disruption has previously been shown to enhance activated T-cell mediated killing, as well as potentiate the effect of immunotherapy in syngeneic tumor models." (PMID 31452512, 2019). "Due to its involvement in the regulation of these oncoproteins, PTPN2 has been suggested to be a tumour suppressor." (PMID 30515568, 2019). "PTPN2 has been proposed as a tumour suppressor, following several deletion and overexpression studies in haematological and solid malignancies." (PMID 31025094, 2019). "PTPN2 low protein expression and copy loss were related to a higher risk of distant recurrence in NHG grade 1 or 2 tumours." (PMID 31025094, 2019). "Patients with low membranous pMet in their tumours and low PTPN2 expression had a poor survival rate, which was also seen in Luminal A disease and patients with tumours overexpressing HER2." (PMID 31025094, 2019). "The protein tyrosine phosphatase PTPN2 dephosphorylates several tyrosine kinases in cancer-related signalling pathways and is thought to be a tumour suppressor." (PMID 31025094, 2019).
tumor (continued). "For instance, by constructing a single-guide RNA (sgRNA) library targeting 2,398 genes and applying genome-wide CRISPR-Cas9 screening in B16 tumor cells, researchers identified protein tyrosine phosphatase non-receptor type 2 as a novel cancer immunotherapy target." (PMID 40487409, 2025). "A small molecule inhibitor, ABBV-CLS-484, and a related compound-182 inhibit PTPN1/PTPN2 with high selectivity over other phosphatases and mediate anti-tumour effects via direct effects on cancer cells and via the enhancement of NK and T cell recruitment and effector function within tumours." (PMID 38334623, 2024). "Efficient PTPN2 depletion was observed after treatment with M(I + D)PH nanoparticles, which resulted in the recruitment of intratumoral infiltrating lymphocytes and an increase of proinflammatory cytokines in the tumor tissue." (PMID 38898493, 2024). "Similarly, PTPN2 acts as a tumour-suppressor protein in T cell leukaemias and triple-negative breast cancer (TNBC) by counteracting oncogenic Src kinase and JAK-STAT signalling." (PMID 38334623, 2024). "Enhanced efficacy of PTPN2-deficient CAR-T cells was associated with elevated Lck and STAT5-dependent cytotoxic T lymphocyte (CTL) function and superior STAT5-dependent and CXC chemokine receptor 3 (CXCR3)-mediated homing of CAR-T cells to tumours." (PMID 38334623, 2024). "Additionally, co-deletion of SOCS1 and PTPN2 in REGNASE-1-null T cells further enhanced anti-tumour immunity by improving mitochondrial function, indicating a promising therapeutic target for cancer immunotherapies." (PMID 38581063, 2024). "Notably, M(I + D)PH treatment showed the greatest inhibitory effect on tumor weight, indicating the synergistic therapeutic efficacy of chemotherapy and the PTPN2 targeted immunotherapy." (PMID 38898493, 2024). "The PTPN2 knockdown efficiency was verified by immunohistochemical staining of the tumor tissues." (PMID 38898493, 2024). "PTPN2/N1 are thus emerging as intracellular checkpoints curbing T-cell-mediated antitumor immunity, positioning PTPN2/N1-targeted therapy at the crux of a dual anti-cancer strategy by directly attacking tumor cells and fortifying the antitumor efficacy of immune cells." (PMID 39065585, 2024). "Consistent with the role of the phosphatases in limiting T cell anti-cancer responses, as described using gene knockout models, PTPN1 and PTPN2 inhibitors have been used to enhance anti-tumour immunity and sensitise tumours to other immunotherapy modalities in pre-clinical models." (PMID 38334623, 2024). "Given our observation of increased antigen presentation in AC484-treated tumour cells both in vitro and in vivo, we next evaluated whether inhibition of PTPN2/N1 elicited changes in the peptide repertoire presented on MHC class I molecules of tumour cells." (PMID 37794185, 2023). "GSEA of AC484 compared with anti-PD-1 or untreated tumours revealed enrichment of an effector T cell signature and the IL2–STAT5 gene signature, a result consistent with increased JAK–STAT signalling caused by PTPN2/N1 inhibition." (PMID 37794185, 2023). "PTPN2 knockout has been shown to increase antigen presentation and T cell anti-tumor toxicity." (PMID 37964355, 2023). "In tumor cells, PTPN2 was shown to enhance antigen presentation and growth arrest." (PMID 37812190, 2023). "Moreover, PTPN2 protein was highly expressed in tumor tissues according to the Clinical Proteomic Tumor Analysis Consortium (CPTAC) project." (PMID 37884566, 2023). "Taken together, these results suggest that in immunologically cold tumors, Compound 182 may elicit synergistic effects on anti-tumor immunity by targeting PTP1B/PTPN2 both in tumor cells and T cells." (PMID 37500611, 2023).
tumor (continued). "The role of PTPN2 as a biomarker in tumor microenvironments was systematically studied." (PMID 37884566, 2023). "Thus, in contrast to current therapies, a PTPN2/N1-targeted therapy would engage a dual anticancer mechanism by acting directly on tumour cells and increasing anti-tumour activity of immune cells." (PMID 37794185, 2023). "It was found that PTPN2 was strongly correlated to six tumor stemness indexes in many cancers." (PMID 37884566, 2023). "Therefore, the deletion of PTP1B or PTPN2 in T cells for the most part phenocopies the effects of systemically administering Compound 182 on tumor growth and TILs." (PMID 37500611, 2023). "Additionally, deletion of the protein tyrosine phosphatase PTPN2 in tumor cells increased the efficacy of the immunotherapy by enhancing the interferon-γ-mediated effects on antigen presentation and growth suppression." (PMID 36829496, 2023). "To explore this further, we also asked if Compound 182 could enhance the repression of tumor growth otherwise achieved by deleting PTPN2 in T cells." (PMID 37500611, 2023). "We theorized that Ptpn2 inhibition might sensitize tumor cells to ICI treatment by increasing IFNγ signaling." (PMID 36968224, 2023). "Indeed, such studies point towards the combined targeting of PTP1B or PTPN2 in tumor cells and T cells, and potentially other immune cells, eliciting synergistic outcomes." (PMID 37500611, 2023). "Our studies indicate that the relative importance of PTP1B/PTPN2 inhibition in tumor cells versus T cells may be dependent largely on the tumor microenvironment." (PMID 37500611, 2023). "Overall, our results suggest that small-molecule inhibitors of PTPN2 may have utility as sensitizing agents to circumvent tumor resistance to ICIs." (PMID 36968224, 2023). "Moreover, the combined deletion of PTPN2 in T cells and treatment with Compound 182 further suppressed tumor growth and/or led to the eradication of 3/6 tumors." (PMID 37500611, 2023). "Therefore, it is likely that the pharmacological targeting of two key negative regulators of this pathway, PTP1B and PTPN2, would for the most part be beneficial and help promote anti-tumor immunity and the response to immunotherapy." (PMID 37500611, 2023). "The deletion of PTPN2 in T cells not only promoted the activation and cytotoxic potential of tumor-infiltrating/resident T cells (as reflected by IFNγ, TNF and GZMB levels), but also enhanced STAT-1 signaling in AT3-OVA tumor cells, the expression of Cxcl9 and the recruitment of T cells." (PMID 37500611, 2023). "Importantly, using genetic approaches we have been able to show that the combined targeting of PTPN2 in tumor cells and T cells in mice can yield even greater anti-tumor immunity." (PMID 37500611, 2023). "Here, the authors demonstrate that inhibition of PTP1B and PTPN2 in tumor cells and T-cells with a small molecule inhibitor represses the growth of immunogenic and cold tumors, and enhances response to anti-PD-1 immunotherapy without promoting immune-related toxicities." (PMID 37500611, 2023). "Moreover, TAFs (tumor-associated fibroblasts) contribute to CRC’s metastasis via secreting TGF-1β and JAK/STAT signaling pathway in CRC, which is inhibited by PTPN2." (PMID 36077422, 2022). "The PTPN2 expression level was significantly increased in CRC tumor tissues of all stages." (PMID 36077422, 2022). "On the one hand, PTPN2 participates in tumor avoidance of immune recognition." (PMID 36077422, 2022). "PTPN2 expression in patients who get PAAD is significantly correlated with tumor stage." (PMID 35154122, 2022). "Many studies have corroborated the role of PTPN2 as a tumor suppressor in cancers." (PMID 36077422, 2022). "Moreover, PTPN2 overexpression reduced the number of tumors and presented a prolonged latency of tumor initiation during skin carcinogenesis using epidermal-specific PTPN2 overexpression mice." (PMID 36077422, 2022).
tumor (continued). "The intervention of PD‐1/PD‐L1 pathway induced by PD‐L1 knockdown as well as the sensitization effect on IFN‐γ mediated by deletion of PTPN2 occurred simultaneously in the tumor, which could cascade amplify the adaptive antitumor immunity." (PMID 34258164, 2021). "Although PTPN2‐deficient CAR T cells were not evident in the contralateral tumour‐negative mammary glands, this is not unexpected as we used virgin mice in our studies." (PMID 31803974, 2020). "The increased CAR T‐cell numbers resulted in a more profound repression of tumour growth irrespective of PTPN2 status, but only PTPN2‐deficient CAR T cells eradicated tumours." (PMID 31803974, 2020). "As expected, we saw higher cytotoxic activity when peptide-loaded and reference target splenocyte populations or antigen-negative and antigen-positive tumor cells were injected into host mice that received PTPN2-deficient OT-I cells." (PMID 32726622, 2020). "Here, we show for the first time that PTPN2 plays a tumor-promoting function in KRAS-driven cancer." (PMID 33122197, 2020). "Moreover, the composition of the immune cell population in the tumor microenvironment was strongly altered in PTPN2-null tumors displaying a higher number of activated and cytotoxic CD8+T cells and γδ+ T cells." (PMID 33003469, 2020). "Indeed, PTPN2 deletion in B16 tumor cells enhanced IFNγ signaling, caused a strong change in the expression profile of IFNγ response gene, and increased phosphorylation of STAT1, thereby reducing tumor growth of PTPN2-null mice." (PMID 33003469, 2020). "Accordingly, we determined whether PTPN2 deficiency might overcome tolerisation and render naive OT‐1 CD8+ T cells capable of suppressing the growth of OVA‐expressing tumours." (PMID 31803974, 2020). "Our data show that PTPN2 plays an important role in the maintenance of KRAS-dependent tumor cells." (PMID 33122197, 2020). "Given that pro-inflammatory responses are thought to be helpful in the suppressive tumor environment, deletion of PTPN2 in CD4 T cells could enhance CD8 T cell-mediated tumor elimination and might also inhibit the development of Tregs." (PMID 33425916, 2020). "Given our findings on PTPN2 in T‐cell‐mediated immunosurveillance and anti‐tumour immunity, we determined whether targeting PTPN2 might enhance the function of CAR T cells in solid tumours." (PMID 31803974, 2020). "This was reliant on PTPN2 deficiency driving the IFNγ‐induced and STAT‐1‐mediated expression of antigen‐presentation pathway genes and T‐cell chemoattractants, such as Cxcl9 in tumour cells." (PMID 31803974, 2020). "To gain insights into the mechanism by which PTPN2 regulates the proliferation and survival of KRAS-dependent tumor cells, we first checked whether PTPN2 affects the KRAS activation, using an RAS-GTP pulldown assay." (PMID 33122197, 2020). "Low PTPN2 protein expression was associated with a higher risk for distant recurrence, this was even more apparent in the Luminal A subtype and tumours with HER2 overexpression, but not in the triple-negative subtype." (PMID 31025094, 2019). "PTPN2 gene deletion was detected in 17.8% (26/146) of the tumours." (PMID 30515568, 2019). "Protein loss was found to be related to worse survival in patients with tumours with NHG 2, with a similar trend for NHG 1, whilst PTPN2 copy loss was associated with worse survival in patients with tumours with NHG 1, neither was associated with DRFS at a high grade." (PMID 31025094, 2019). "Whilst PTPN2 copy loss did not correlate to any of the clinicopathological parameters, low PTPN2 protein expression was found to be correlated with ER-negative tumours and pAkt status in the cytoplasm." (PMID 31025094, 2019).